Y_RNA (Y RNA )
Gene: Miscellaneous RNA gene on chromosome 2 (69,334,600 to 69,334,692, forward strand). Ensembl gene ENSG00000252250.
Homologues: Orthologues: chimpanzee Y_RNA (98% identical). Paralogues in human: RNY4 (85% identical), RNY4P19 (84% identical), RNY4P25 (82% identical), RNY4P6 (82% identical), RNY4P7 (82% identical), Y_RNA (81% identical), RNY4P13 (80% identical), RNY4P23 (80% identical), RNY4P37 (80% identical), Y_RNA (80% identical), RNY4P10 (78% identical), RNY4P3 (78% identical), and 89 more.